DNAJC8 (DnaJ heat shock protein family (Hsp40) member C8)
Description:
Suppresses polyglutamine (polyQ) aggregation of ATXN3 in neuronal cells.
Synonyms: SPF31; HSPC331
Tractability: Small molecule: a structure with a bound ligand is known. PROTAC: ubiquitination databases record sites on it; its protein half-life has been measured.
Gene: Protein-coding gene on chromosome 1 (28,199,456 to 28,233,032, reverse strand). Ensembl gene ENSG00000126698.
Subcellular location: Nucleus
Subcellular location (Human Protein Atlas): Nucleoplasm; Cytokinetic bridge; Cytosol
Pathways (Reactome):
Metabolism of RNA: mRNA Polyadenylation; mRNA Splicing - Major Pathway
Disease: Dengue Virus-Host Interactions
Gene Ontology:
Molecular function: Hsp70 protein binding; protein binding
Cellular component: nucleoplasm; nucleus
Genetic constraint (gnomAD): Loss-of-function variants: 19 observed, 38.01 expected, observed/expected ratio (o/e) 0.5, 90% interval 0.35 to 0.73. The upper end of that interval is the gene's LOEUF score, 0.73, which puts it in group 3 of 6, group 1 being the genes least tolerant of losing a copy. Missense variants: 196 observed, 292.89 expected, observed/expected ratio (o/e) 0.67, 90% interval 0.6 to 0.75. Synonymous variants: 79 observed, 96.79 expected, observed/expected ratio (o/e) 0.82, 90% interval 0.68 to 0.98.
Homologues: Orthologues: chimpanzee DNAJC8 (100% identical), macaque DNAJC8 (99% identical), guinea pig DNAJC8 (99% identical), mouse Dnajc8 (99% identical), dog DNAJC8 (98% identical), rat Dnajc8 (92% identical), pig DNAJC8 (91% identical), tropical clawed frog dnajc8 (86% identical), zebrafish dnajc8 (81% identical), Drosophila melanogaster CG10375 (51% identical), Caenorhabditis elegans dnj-30 (44% identical).
Diseases named in the same sentence as DNAJC8 in open-access papers:
DNAJC8 is named in the same sentence as 8 diseases in open-access papers, as found by Europe PMC text mining. Sharing a sentence is not in itself a finding about the gene and the disease. The quoted sentences say what the papers report.
breast carcinoma (2 papers, 2021). "In the breast cancer cell group, THRAP3, DNAJC8, and RPL13A were the three most stably expressed genes, while TUBA1A, B2M, and ACTB were the least stably expressed genes." (PMID 34895237, 2021). "According to the ΔCt method, TRA2B, RHOA, and THRAP3 were the most stably expressed genes, while DNAJC8, GAPDH, and B2M were the least stable genes in the breast cancer tissue group, which was consistent with the analysis according to NormFinder." (PMID 34895237, 2021). "In the breast cancer tissue group, the three most stably expressed genes (with the lowest M values) were SF1, THRAP3, and TARDBP, while GAPDH, DNAJC8, and B2M were the least stably expressed genes." (PMID 34895237, 2021). "In the breast cancer tissue group, TRA2B, RHOA, and THRAP3 were the most stable genes, and DNAJC8, GAPDH, and B2M were the most unstable genes." (PMID 34895237, 2021).
cancer (2 papers, 2020 to 2023). A tumor composed of atypical neoplastic, often pleomorphic cells that invade other tissues. "Therefore, the high expression of DNAJC8 is significantly related to immunosuppression microenvironment of cancer and detailed experimental investigation is needed in the future." (PMID 38274804, 2023). "In the HSP40 family, DNAJC25 and DNAJC8 were positively associated with stemness in 16 and 14 cancers, respectively, while DNAJC11 and DNAJC3 were negatively associated with stemness in 25 and 25 cancers, respectively." (PMID 33225964, 2020). "Therefore, DNAJC8 is also likely to be involved in modulation of cancer metastasis." (PMID 38274804, 2023). "DnaJ heat shock protein family member C8 (DNAJC8), belonging to the heat shock protein 40 (HSP40) family, is known to regulate cancer biology function." (PMID 38274804, 2023). "However, there is still a lack of research on DNAJC8, especially on its role in cancer." (PMID 38274804, 2023).
tumor (1 paper, 2023). "These indicate that DNAJC8 is associated with tumor immunosuppressive microenvironment." (PMID 38274804, 2023). "Meanwhile, immunohistochemical result further confirmed the upregulated DNAJC8 expression in the tumor tissues." (PMID 38274804, 2023). "Furthermore, there was an upward trend of DNAJC8 expression in patients with advanced stage tumor (p<0.05) and vascular invasion (p<0.05)." (PMID 38274804, 2023). "In fact, clinical correlation analysis indicated that DNAJC8 expression was closely related to vascular invasion, and the HSP40 family had been proved to play an important role in tumor metastasis." (PMID 38274804, 2023). "DNAJC8 promotes the proliferation and inhibits apoptosis of HCC cells and interferes with the tumor immune response." (PMID 38274804, 2023). "In addition, immune checkpoint molecular expression analysis also confirmed that five immune checkpoint molecular were significantly positively correlated with DNAJC8 expression, suggesting that DNAJC8 may promote tumor immune escape through checkpoint pathway." (PMID 38274804, 2023). "DNAJC8, a member of HSP40 family, reports about its functional effects especially in tumor are scarce." (PMID 38274804, 2023).
DNAJC8 also shares sentences with these, for which no sentence is quoted: hepatocellular carcinoma (1 paper); neuroblastoma (1); osteosarcoma (1); pancreatic cancer (1); Spinocerebellar ataxia type 3 (1).